RPS4X (ribosomal protein S4 X-linked)
Diseases named in the same sentence as RPS4X in open-access papers (continued):
Sharing a sentence is not in itself a finding about the gene and the disease.
tumor (18 papers, 2010 to 2025). "Although RPS4X is implicated in tumor progression in several cancers, its extraribosomal functions remain poorly characterized, and it is unknown whether RPS4X affects the ubiquitination of other substrates of the SCF complex." (PMID 41154579, 2025). "Although the cause of perturbed RPS4X expression in these tumor clusters is unknown, altered methylation patterns on chromosome X have been described in different subsets of cancers and could be responsible for the expression patterns detected by t-SNE." (PMID 29530001, 2018). "Because nucleolar stress is frequently observed in rapidly growing tumor cells, it is possible that cancer cells exploit the function of RPS4X to overcome these stressful conditions." (PMID 41154579, 2025). "Our findings suggest that RPS4X contributes to tumor progression by stabilizing anti-apoptotic proteins and promoting resistance to cell death." (PMID 41154579, 2025). "Based on these criteria and supporting literature, HNRNPM, RPL4, and RPS4X were prioritized for further validation due to their reported involvement in tumor progression or chemoresistance." (PMID 40476445, 2025). "Recently, it has been reported that most rectal colon cancer cell lines express high levels of RPS4X and that the expression levels are negatively correlated with tumor prognosis." (PMID 39199272, 2024). "In view of these reports and our findings in the present study, an enhancement in MDM2 protein stability by RPS4X could potentially lead to tumor progression and poor prognosis." (PMID 39199272, 2024). "Taken together, we inferred that GTF2E2 led to tumor progression via the interaction with RPS4X." (PMID 33757492, 2021). "To decipher the mechanism by which GTF2E2 regulates LUAD’s development, using CO-IP and IC-MS/MS analyses, we identified RPS4X, whose potential function in tumor development had been widely reported previously, as an essential factor in GTF2E2-mediated tumor progression." (PMID 33757492, 2021). "Interestingly, some of our tumor clusters with altered RPS4X expression were comprised of a greater proportion of females than males, perhaps reflecting RPS4X’s residence on the X chromosome." (PMID 29530001, 2018). "Low expression of RPS4X correlated significantly with tumor stage." (PMID 23800275, 2013). "As for the hub RPS4X, it has been proven that dysregulation of RP expression occurs in a variety of human diseases, notably in many cancers, and altered expression of some RPs correlates with different tumor phenotypes and patient survival, including the prostatic one." (PMID 37021928, 2023). "Future studies examining the co-expression of RPS4X, MCL1, and HAX1 in clinical tumor samples, as well as functional studies in patient-derived models, will be essential to validate the potential oncogenic role of RPS4X." (PMID 41154579, 2025). "The overexpression of RPS4X in both A549 and H1299 cell lines generated an opposite effect compared with GTF2E2 knockdown, leading to increased tumor cell proliferation and migration as well as tumorigenesis." (PMID 33757492, 2021). "Considering the critical role that mTOR signaling pathway plays in multiple tumor types, this novel discovery prompted us to wonder whether a similar mechanism exists in LUAD when RPS4X is activated by upstream molecules, like GTF2E2." (PMID 33757492, 2021). "Furthermore, in vitro and in vivo experiments showed that SLFN11 likely functions as a tumor suppressor in HCC progression and metastasis by targeting RPS4X via the mTOR signaling pathway." (PMID 32292519, 2020). "Specifically, a group of 40 well-defined genes, classified according to their function, were able to distinguish between 2 different GBM signatures revealing the possible different proliferative potential in high grade GBM tumours (VIM, GLUL, PLK1, HUWE1, RPS4X...)." (PMID 20735813, 2010).
tumor (continued). "Specifically, about 77% of the tumor tissues (72 of 94) with low SLFN11 expression showed moderate or strong RPS4X staining and 64% (56 of 88) of those with high SLFN11 expression displayed negative or weak RPS4X staining." (PMID 32292519, 2020). "Unlike RPL3 and RPS4X, RPL13’s role in tumor development is less clear." (PMID 29530001, 2018).
cancer (16 papers, 2010 to 2025). A tumor composed of atypical neoplastic, often pleomorphic cells that invade other tissues. "RPS4X has been implicated in a worse prognosis in various cancer types, which is likely linked to RPS4X regulation of cell proliferation." (PMID 40649992, 2025). "Altered RPS4X expression, found in six cancer cohorts, associated with unique expression of nine other RPTs, strongly suggesting an underlying coordinated expression, the mechanism of which remains to be identified." (PMID 29530001, 2018). "In addition to RPL11, our study highlights several other ribosomal proteins that have been implicated in cancer progression, such as Ribosomal Protein S4 X (RPS4X) and eukaryotic translation initiation factor 3 subunit i (eIF3i)." (PMID 39891297, 2025). "RPS4X is involved in various biological pathways in cancer cells via direct or indirect interaction with other genes." (PMID 33757492, 2021). "Other recurrent RPT expression patterns across cancer cohorts involved RPS4X, RPL13, RPL8 and RPL30." (PMID 29530001, 2018). "Some other genes differentially expressed in this pool of cells CD133+ and also involved in cancer and neurological disease are RPS4X, RPS3A or TUBA1B." (PMID 20735813, 2010). "Subsequently, to define whether endogenous RPS4X interacted with MDM2 in human cancer cells, we conducted a co-immunoprecipitation assay using HeLa cells." (PMID 39199272, 2024). "To determine whether GTF2E2 signals through RPS4X to mediate cancer cell proliferation, we further knocking down GTF2E2 in RPS4X-OE-A549 cells." (PMID 33757492, 2021). "Besides, the prognostic value of RPS4X has also been reported in several cancer types." (PMID 33757492, 2021). "More precisely, cancer cells with low expression of RPS4X present in high-grade tumors that have never been in contact with platinum would correspond to cells exhibiting a pre-existing mechanism for resistance to such a drug." (PMID 23800275, 2013). "Further studies are required to elucidate the functional consequences of the interaction between RPS4X and MDM2 in cancer cells and may contribute to reinforcing the evidence that it could be a biomarker for these cancers, which may help in more effective treatment for patients." (PMID 39199272, 2024).
infection (9 papers, 2007 to 2025). The state of being infected such as from the introduction of a foreign agent such as serum, vaccine, antigenic substance or organism. "Of these genes, ribosomal protein genes such as RPS4X and RPS6 also showed downregulation in expression levels, suggesting the importance of ribosomal protein genes during infection." (PMID 35464437, 2022).
neurological disease (2 papers, 2006 to 2010). "Our analysis revealed that the human RPS4X, RPS15A, and RPLP0 genes are located in chromosomal regions linked to brain or neurological disorders, and brain regions were affected in the morphants for these genes." (PMID 17183665, 2006).
RPS4X also shares sentences with these, for which no sentence is quoted: acute myeloid leukemia (1 paper); adenovirus infection (1); autoimmune disease (1); bladder cancer (1); chronic lymphocytic leukemia (1); congenital heart disease (1); developmental delays (1); Diamond-Blackfan Anaemia (1); glioma (1); hematological malignancies (1); hypothyroidism (1); latent infection (1); leukemia (1); lung carcinoma (1); Myelodysplasia (1); nonalcoholic steatohepatitis (1); Obesity (1); osteosarcoma (1); pancreatic cancers (1); prostate carcinoma (1); psoriasis (1); tetanus (1).